IL6 (interleukin 6)
Diseases named in the same sentence as IL6 in open-access papers (continued):
Sharing a sentence is not in itself a finding about the gene and the disease.
anemia (continued). "Rapid Hb levels and systemic inflammation improvement following tocilizumab therapy align with previous reports highlighting the effectiveness of targeting IL-6 in AOSD-related anemia." (PMID 40065895, 2025). "First, a randomized study showed that 24-week pre-dialysis resistance training (RT) (1 h before HD, 3×/week) reduced sarcopenia and improved strength, body composition, functional performance, and biomarkers (TNFα, IL-6, anaemia)." (PMID 41126503, 2025). "Coefficients for the effects of changes in IFN-γ, IL-6, IL-10 and neutrophils on the likelihood of recovery from anemia." (PMID 41306959, 2025). "Among the causes, iron deficiency anemia (IDA) is the most frequent, often compounded by anemia of chronic disease, driven by inflammatory cytokines such as interleukin-6 that alter iron homeostasis through hepcidin upregulation." (PMID 41458685, 2025). "As a pro-inflammatory cytokine, IL-6 contributes to the development of anemia by inhibiting erythropoiesis and promoting iron sequestration through the induction of hepcidin production." (PMID 40429405, 2025). "Inflammation and suppression of erythropoiesis resulting from pro-inflammatory cytokines such as IL-6 are leading mechanisms of anemia in cancer patients." (PMID 40004836, 2025). "Secondly, aflatoxin exposure can induce the release of inflammatory markers, such as interleukin 6 (IL-6), which can suppress the erythropoiesis process and lead to anaemia." (PMID 40077727, 2025). "Inflammatory cytokines like IL-6 contribute to anemia by promoting hepcidin production, which restricts intestinal iron absorption and sequesters iron in macrophages, resulting in IDA." (PMID 40337739, 2025). "Concurrently, infection-induced cytokine storms (IL-6, hepcidin upregulation) disrupt erythropoiesis and iron metabolism, establishing anemia of chronic disease." (PMID 41487654, 2025). "IL6 contributes to anemia by stimulating hepatocytes to upregulate hepcidin transcription through activation of the JAK/STAT3 pathway, which acts as a negative regulator of iron absorption in the duodenum and iron release from macrophages." (PMID 40427188, 2025). "The significant decrease in IL-6 can be an indicator in decreasing hepecidin levels that leads to better enhancement in serum iron levels and treatment of anemia resulted from CKD." (PMID 39910177, 2025). "Studies have shown that IL‐6, frequently increased in cancer, induces hepcidin production, leading to hypoferremia and anemia." (PMID 40791284, 2025). "Studies have shown that the severity of anemia in TB patients can correlate with markers of disease activity, such as elevated inflammatory cytokines (e.g., interleukin 6 (IL-6) and tumor necrosis factor alpha (TNF-α)) and C-reactive protein (CRP) levels." (PMID 40698207, 2025). "The successful use of IL-6 inhibitor therapy emphasizes the role of cytokines in chronic disease anemia and systemic inflammation in AOSD." (PMID 40065895, 2025). "Our results show that sRAGE is involved in anemia of the chronic inflammatory process, as positive correlations between sRAGE and prohepcidin and IL-6 (an inducer of hepcidin synthesis) were established only in the subgroup of patients with ACD." (PMID 39684440, 2024). "Anemia can result from the body’s secretion of cytokines during an illness, including IL-1 and IL-6, which can prevent the bone marrow from producing RBC." (PMID 38896174, 2024). "The higher inflammatory response in piglets without additional iron in the diet in this study is consistent with previous studies in which low iron status led to increased pro-inflammatory cytokines (including IL-1β, IL-6, and TNF-α) in iron deficiency anemia." (PMID 39296492, 2024). "Children with severe malarial anemia had higher plasma levels of TNF‐α (p < .001), IFN‐ɣ (p < .001), IL‐1β (p < .001), IL‐6 (p < .001), GM‐CSF (p < .001), and IL‐10 (p < .001) than those with malaria only, and mild/moderate anemia." (PMID 39240033, 2024).
anemia (continued). "Various studies showed that the inflammatory cytokines IL-6 and TNF-α played crucial roles in the development of cancer-associated anemia and cachexia." (PMID 39372868, 2024). "Chronic hyperglycemia increases the expression of proinflammatory cytokines such as interleukin-6, which has antierythropoietic effects leading to development of anemia." (PMID 39541418, 2024). "Regarding ACD, it is a type of normocytic normochromic anemia that arises from inflammatory conditions whereby the IL‐6–hepcidin axis is triggered, leading to low serum iron levels but maintaining sufficient iron stores." (PMID 39055215, 2024). "Studies have shown that joint mobility is more severe in RA patients with anemia, interleukin-6 (IL-6), CRP, and CCP levels are significantly elevated in anemic RA patients compared to non-anemic RA patients, indicating high disease activity." (PMID 39136015, 2024). "We obtained the following parameters: serum creatinine and urea; the inflammation markers CRP (C-reactive protein) and IL-6 (interleukin-6); and the anemia markers complete blood count, serum ferritin, and transferrin saturation (TSAT)." (PMID 39200365, 2024). "In the HD group, the plasma KIM-1 levels showed a statistically notable correlation with inflammation (mean CRP: R = 0.28, p = 0.02; IL6: R = 0.36, p = 0.005) and with anemia (hematocrit: R = −0.5, p = −0.0316; hemoglobin: R = −0.5, p = 0.02)." (PMID 39200365, 2024). "Activated IL‐6 induces acute phase inflammatory reactions, such as fever and anemia, and promotes B cell differentiation to form antibodies." (PMID 38578001, 2024). "There is growing evidence that wildfire smoke induces inflammation in pregnant women, indicated by elevated CRP, IL8, IL6, MCP-1, neutrophils, and monocytes, and that biofuel exposure in pregnant women from India has been associated with anemia." (PMID 38892681, 2024). "Through the analysis of several clinical and laboratory parameters, we observed that those with severe anemia exhibited greater systemic inflammation, characterized by high concentrations of IL-8, IL-1RA and IL-6." (PMID 37143662, 2023). "The involvement of IL-6 in the production of hepcidin contributes to the development and aggravation of anemia of inflammation." (PMID 37143662, 2023). "Both female Cish genotypes exhibited similar elevations of specific cytokines, including those associated with anemia, such as TNF-α and IL-6, with only IL-18 levels higher in Cish+/+ mice following infection." (PMID 38029163, 2023). "During infection, hepcidin expression is upregulated by cytokines such as interleukin-6 (IL-6), leading to the characteristic hypoferremia and hyperferritinemia seen in anemia of inflammation." (PMID 37238418, 2023). "Anaemia of chronic diseases, resulting from the activation of pro-inflammatory cytokines such as interferon alpha, interleukin 6 and tumor necrosis factor alpha, is also often diagnosed in IBD." (PMID 37048531, 2023). "Apart from these previous episodes, he also suffered from systemic lymphadenopathy, anemia, elevated C-reactive protein, polyclonal hypergammopathy, and elevated interleukin (IL)-6." (PMID 36873956, 2023). "Hepcidin expression is upregulated by inflammation and it has also been shown that interleukin-6 enhances the hepatic synthesis of hepcidin, which regulates iron recycling, leading to the development of anemia due to hypoferremia." (PMID 37763711, 2023). "Nevertheless, both IL-10 and IL-6 have been reported to be lower in severe anemia compared with uncomplicated malaria, which indicates the dual role of IL-6 and IL-10 in anti-inflammatory processes." (PMID 36668942, 2023). "The increased levels of CRP, anemia, and reduced levels of albumin are also due to increased level of IL-6, which leads to myocardial infarction and an extra-articular manifestation of RA." (PMID 37113751, 2023). "IL-6 induces hepcidin production, thus demonstrating the downstream effect of IL-1 inhibition on anemia." (PMID 37764213, 2023).
anemia (continued). "Antibody-mediated neutralization of IL-6 reversed anemia, extending survival, and IL-6 promotes MDS progression to AML." (PMID 36809258, 2023). "The main cause of hyporesponsiveness to ESA is the systemic inflammation of CKD, known as inflammation anemia, a key role being played by IL-6." (PMID 35624853, 2022). "In contrast, IFN-γ production was lower in anemic patients, suggesting that even if both cytokines are up-regulated in active TB, IL-6 was specifically related to anemia of inflammation and progression of TB disease." (PMID 36014824, 2022). "Other cytokines, including TNF-α, IL-1, and IL-6, lead to the expansion of CECs and enrichment of early-stage CECs by impairing erythropoiesis and aggravating anemia." (PMID 35251018, 2022). "They found that clinical symptoms, such as low-grade fever, abdominal/lumber pain, and anemia, IL-6 and C-reactive protein (CRP) were significantly higher in IgG4-AAs and IgG4-PA than in IgG4-RF." (PMID 35440292, 2022). "Counteracting anorexia and anemia and limiting the action of inflammatory cytokines, particularly IL-6, should be part of any strategy to correct this illness." (PMID 35159388, 2022). "Still, anemia, CRP, and IL-6 were significantly associated with prematurity in SARS-CoV-2-infected pregnant women in our study." (PMID 36579593, 2022). "Higher levels of inflammatory markers, IL-6, leptin, hepcidin, ferritin, and ROS all contribute to anemia in cancer subjects." (PMID 36558514, 2022). "An analysis of the Rhumadata® clinical database and registry confirmed that the improvement in anemia observed with IL-6 inhibitors was “numerically and statistically superior” to TNF inhibitors." (PMID 36008838, 2022). "The presence of chronic atrial fibrillation, previous cancer, IL-6 > 40 pg/mL, and anemia were independent predictors of death." (PMID 35172759, 2022). "Compared with standard ferrous sulphate treatment (329.7 mg/day), 100 mg of 20–30% iron-saturated BL was found to be a more effective treatment for anemia and AI across all groups through its ability to downregulate IL-6." (PMID 35057548, 2022). "IL-6 appears to be the central mediator of anemia in chronic disease, through its induction of hepcidin production." (PMID 36544236, 2022). "Multiple studies have shown that an elevated serum level of IL-6 was positively correlated with various markers of weakness, such as slow walking speed, low muscle strength, and anemia." (PMID 35111851, 2022). "Another IL-6 inhibitor, tocilizumab, was used to treat inflammation-induced anemia in cancer patients with good clinical effect." (PMID 36558477, 2022). "We strongly recommend recording baseline and post-RT iron studies and anemia levels as well as hepcidin and IL-6 levels whenever possible for all prospective studies utilizing cetuximab concomitant with RT so that we can have a definite conclusion." (PMID 35672745, 2022). "In states of anemia due to chronic disease, reactive thrombocytosis occurs through cytokines such as IL-6 and thrombopoietin." (PMID 35629394, 2022). "As a result, chronic IL-6 elevation is involved in the development of anaemia, among other things, by increasing hepcidin production and thus serum hepcidin levels." (PMID 36612220, 2022). "Systemic inflammation, mediated by inflammatory cytokines such as tumor necrosis factor-alpha (TNF-α), interleukin-1 (IL-1), interleukin-6 (IL-6), and interferon- (IFN- γ), is a well-known cause of anemia." (PMID 35984839, 2022). "IL-6 overexpression can induce other complications, including fever, vascular leakage, anemia, cardiomyopathy, acute kidney injury (AKI), interstitial edema, and myocardial dysfunction." (PMID 35464491, 2022). "IL-6 involvement in RA pathogenesis includes B-cell proliferation, matrix metalloproteinase expression, acute-phase response and anaemia." (PMID 35886067, 2022). "The report confirms that patients with RA have a significant elevation of serum IL-6 levels including the patient group with anemia." (PMID 36008838, 2022).
anemia (continued). "On adjusted logistic regression analysis, atrial fibrillation, history of cancer, and high IL-6 levels remained significant, while anemia remained borderline." (PMID 35172759, 2022). "The cytokine-induced inhibition of erythropoiesis is regarded as an important mechanism for the development of anemia in cancer patients, TNFα in particular but also other inflammatory regulators, including IL1β, IL6, IL10 and IFNγ, probably contribute." (PMID 35160156, 2022). "As a result of the stimulation of hepcidin by proinflammatory cytokines and, most notably, interleukin (IL)-6, anemia occurs because iron is retained in the cells, and its flow into the plasma decreases." (PMID 35892443, 2022). "In an un-stratified multiple logistic regression analysis of these significant factors, −a/−a thalassemia and higher levels of IL-6 and TNF-RII independently increased, whereas higher levels of TNF-RI and sTfR decreased, the risk of fetal anemia." (PMID 33995348, 2021). "Other mechanisms of anemia induced by IL-6 include rapid hemodilution, impairment of erythroid proliferation, and maturation and downregulation of the membrane-bound erythropoietin receptor." (PMID 33535417, 2021). "For example, increased levels of cord IL-6 increased the odds and cord TNF-RI decreased the odds of fetal anemia, but only when the mother was iron-deficient." (PMID 33995348, 2021). "In patients receiving canakinumab—an antibody that is targeting IL-1β—hsCRP and IL-6 levels decreased while hemoglobin levels increased concomitantly in patients with baseline anemia." (PMID 34458328, 2021). "Elevated fetal IL-6 was reported in fetal anemia due to maternal Rh alloimmunisation, and presumed to be a marker of fetal systemic inflammatory response syndrome (SIRS) secondary to red blood cell destruction in the reticuloendothelial system." (PMID 33995348, 2021). "Strategies to reverse this condition should consider two factors: counteracting anorexia and anemia, and inhibiting the activity of inflammatory cytokines, particularly IL-6." (PMID 33809200, 2021). "In children affected by MIS-C, additional laboratory abnormalities detected are neutrophilia, mild anemia, thrombocytopenia, hypoalbuminemia, hypertriglyceridemia, and increased interleukin-6 (IL-6) levels." (PMID 34959805, 2021). "The central role played by IL-6 in inducing cancer-related anemia and its relationships with the incidence and severity of muscle wasting is noteworthy." (PMID 33809200, 2021). "We measured plasma levels of inflammatory and anti-inflammatory cytokines that have been previously implicated in the pathogenesis of anemia (TNF-α and its receptors (soluble TNF-RI and TNF-RII), IFN-γ, IL-6, and IL-10) in cord blood." (PMID 33995348, 2021). "In many models of anemia of inflammation, IL-6 has been shown to be a primary driver for hepcidin induction and the SMAD1/5/8 pathway is also known to contribute, likely via activin B and STAT-3-SMAD interactions at the hepcidin promoter." (PMID 34873429, 2021). "According to their review, proinflammatory cytokines such as interleukin-6 increase hepcidin levels during acute and chronic inflammation, which leads to iron-restricted erythropoiesis and anemia of inflammation." (PMID 33801005, 2021). "IL-6 is a cytokine that induces fever, leukocytosis, thrombocytosis, chronic disease anemia, and increased acute phase reactants, including CRP, ESR, and serum amyloid A." (PMID 34041254, 2021). "A connection of IL6 to erythroid maturation, anemia, and inflammation through impairment of mitochondrial function was also established." (PMID 32665031, 2020). "Hepatic peptide hormone hepcidin, a key regulator of iron metabolism, is induced by inflammatory cytokine interleukin-6 (IL-6) in the pathogenesis of anemia of inflammation or microbial infections." (PMID 32545266, 2020).
anemia (continued). "This would be expected, based on the ‘anaemia of chronic inflammation’ mediated by the effects of high levels of IL-6 and as a consequence of hepcidin, resulting in higher iron trapping within macrophages and liver cells." (PMID 32385656, 2020). "Non-survivors in our study had higher levels of inflammatory markers (WBC, procalcitonin, CRP, and IL-6) as well as lower anemia related parameters (RBC, hemoglobin, and hematocrit), which concurs with current publications." (PMID 33198124, 2020). "When calculating for associations between anemia and iron metabolism variables with immune activation upon admission, anemic patients had significantly higher CRP, IL-6 and PCT levels." (PMID 32751400, 2020). "When stratified by severity, we found that patients with severe infections were more likely to have anemia, decreased activated partial thromboplastin time, calcium, and albumin, and increased D-dimer and interleukin-6 (P < 0.05)." (PMID 32582740, 2020). "Further, this M1 polarization was associated with cancer-related anemia and was correlated with the severity of anemia, IL-6 levels, and iron metabolism changes, which, as we have already demonstrated, are typical of advanced stage ovarian cancer patients." (PMID 32269279, 2020). "The main objective of this study was to assess the role of IL-6 and hepcidin in the development of anemia of chronic disease in Egyptian patients." (PMID 32095285, 2020). "Within 2 weeks following complete lymph node excision, there was normalization of IL-6 level and resolution of her leukocytosis, anemia, and thrombocytosis; proteinuria and NT-proBNP reduced within 2 months of surgery." (PMID 32028407, 2020). "In the present investigation, we analyzed IL-6 gene polymorphism in chronic HCV seropositive Egyptian patients on regular HD to evaluate the association between IL-6 and anemia markers." (PMID 32720970, 2020). "Treatment that blocks IL-6 is effective in RA with anaemia, such as the IL-6 receptor blocker tocilizumab." (PMID 33198544, 2020). "The LPS + PM group showed increased BALF leukocytes, characterized by increased macrophages, increased IL-1β and IL-6 levels, anemia and thrombocytopenia." (PMID 32943719, 2020). "A major consequence of IL-6 activity is the overproduction of hepcidin, which in turn decreases iron utilization and absorption from the gut, resulting in anemia and low hemoglobin levels." (PMID 32292672, 2020). "Anemia in cancers is well-documented and is attributed largely to the release of inflammatory cytokines (interleukin 6 (IL-6) in particular)." (PMID 32292672, 2020). "IL-6, anemia, leukocytosis, and thrombocytosis resolved or normalized 2 weeks after resection; creatinine normalized 9 months postsurgery." (PMID 32028407, 2020). "Anemia, decreased activated partial thromboplastin time, calcium, and albumin, and increased D-dimer and interleukin-6 were more frequent in severe disease." (PMID 32582740, 2020). "Labs are usually pertinent for anemia, thrombocytopenia, hyper-gammaglobulinemia, elevated hepatic transaminases, and IL-6." (PMID 32399323, 2020). "While the mechanisms driving anemia of chronic disease are not fully understood, glucocorticoids and inflammatory factors such as interleukin-6 (IL-6) and the IL-6–hepcidin axis are believed to be involved." (PMID 31068843, 2019). "Mechanistically, anemia is directly involved with increased levels of IL-6 and reveals an inverse relationship between hemoglobin and IL-6 in frail patients, with elevated levels of IL-6 directly inhibiting erythropoietin or interfering with iron metabolism." (PMID 31533354, 2019). "Mechanistically, cancer-induced anemia is caused by the secretion of inflammatory factors, such as tumor necrosis factor (TNF)-α and interleukin-6 (IL-6)." (PMID 30641920, 2019). "In inflammation, there is increased production of IL-6, which induces hepcidin production that leads to hypoferremia eventually resulting in anemia." (PMID 31597392, 2019).